PCSK1 (proprotein convertase subtilisin/kexin type 1)
Diseases named in the same sentence as PCSK1 in open-access papers (continued):
Sharing a sentence is not in itself a finding about the gene and the disease.
Obesity (continued). "Nevertheless, further studies with larger sample sizes would be required to provide definite evidence for the association between common variants in PCSK1 and obesity in Chinese Hans." (PMID 20498726, 2010). "This patient shows that PCSK1 abnormalities could have an association with individuals who have hyperphagia and significant obesity, but normal HbA1c and LDL levels." (PMID 41768936, 2026). "Despite this, the truncating nature of the identified PCSK1 variant suggests a potential loss of enzyme function, increasing the likelihood that it could cause obesity even in a heterozygous state." (PMID 40523925, 2025). "PCSK1 gene mutation has been linked to various endocrine disorders, including KS, metabolic disturbances, increased appetite, insulin dysregulation, and potential predispositions to obesity." (PMID 40724652, 2025). "Finally, in terms of clinical significance, the PCSK1 p.Asn221Asp variant has been associated with BMI quantitative trait locus 12, highlighting its potential contribution to obesity risk." (PMID 40281302, 2025). "Notably, certain genes such as MC4R, BDNF, and PCSK1 are implicated in both monogenic and polygenic obesity, depending on the type and frequency of the variant." (PMID 40281302, 2025). "Similarly, studies on PCSK1 have shown that specific mutations lead to a deficiency in proinsulin processing, resulting in hyperphagic obesity." (PMID 38674329, 2024). "Humans with loss-of-function PCSK1 mutations may present a syndrome that comprises obesity, hypogonadotropic hypogonadism, diarrhea, abnormal thyroid and adrenal function, and impaired regulation of systemic glucose levels." (PMID 39876968, 2024). "In addition, PCSK1 was associated with obesity (p = 1.0 × 10−4) and metabolic syndrome (p = 3.0 × 10−3), whereas PPARG1 was associated with obesity (p = 0.044)." (PMID 37761915, 2023). "Furthermore, associations between PCSK1 allelic variants and obesity have been reported in Chinese and Taiwanese subjects." (PMID 37761915, 2023). "Our findings support that the G allele rs6235 of PCSK1 may be a determinant factor in developing obesity and obesity-related metabolic trait changes in Mexican subjects." (PMID 37761915, 2023). "In addition, PCSK1 variants are associated with extreme obesity, impaired glucose tolerance, and polycystic ovarian syndrome." (PMID 36997916, 2023). "Rare mutations in PCSK1 have also been implicated in early monogenic obesity." (PMID 37954272, 2023). "Another important takeaway from GWAS is the fact that numerous common polymorphisms associated with polygenic obesity in ethnically diverse population have been found in genes like PCSK1, MC4R [43••] and POMC, known to carry rare loss of function variants leading to non-syndromic monogenic obesity." (PMID 37819541, 2023). "Although several human PCSK1 mutations have been associated with obesity and two human single nucleotide variants (SNVs) were linked with abnormal lipids in lipoprotein particles, the effect of PCSK1 on lipid and cholesterol metabolism remained largely unclear." (PMID 34996527, 2022). "The compound heterozygous carriers of pathogenic genetic variants in the autosomal recessive genes LEP, LEPR, POMC and PCSK1 are rare, obesity-associated variants in the autosomal dominant gene MC4R are the most common, with 0.8% of participants in our study carrying a variant in MC4R." (PMID 35574020, 2022). "The rs6232 polymorphism of the gene that codes for PCSK1 has also been associated with both childhood and adult obesity; likewise, the rs2229616 polymorphism of the MC4R gene has been associated with an increased risk of developing type 2 diabetes mellitus in Saudi patients." (PMID 35741707, 2022). "Likewise, state-of-the-art literature concerning the role of rare heterozygous PCSK1 variants implies them to be rarely associated with monogenic obesity, as first-degree carrier relatives of patients with PC1/3 deficiency are mostly not reported to be obese." (PMID 36292633, 2022).
Obesity (continued). "Specifically for rare heterozygous PCSK1 variants, the possibility of a dominant negative effect should also be taken into account, as a recent study has identified two rare heterozygous PCSK1 variant carriers that were affected with severe obesity as well as unspecified chronic diarrhea." (PMID 36292633, 2022). "Single nucleotide polymorphisms in the PCSK1 gene have been correlated with obesity predisposition." (PMID 36532520, 2022). "Mutations in PCSK1 have been associated with obesity predisposition." (PMID 36532520, 2022). "Likewise, the other two DEGs identified in the present study—PPARGC1A (peroxisome proliferator-activated receptor-γ co-activator-1alpha) and PCSK1N (proprotein convertase subtilisin/kexin type 1 inhibitor)—have been associated with obesity in humans." (PMID 32485856, 2020). "Food intake drives obesity in strains deficient for melanocortin 2 receptor accessory protein 2, Mrap2-/-, carboxypeptidase E, Cpe-/-, proprotein convertase 1, Pcsk1+/-, or growth differentiation factor 15, Gdf15-/-." (PMID 32356724, 2020). "Finally, although appealing, these new approaches for the treatment of hyperphagia and obesity in PWS and PCSK1 deficiency will have to prove their therapeutic potential in general obesity." (PMID 29880780, 2018). "In this review we will not only discuss the mechanisms by which PWS and PCSK1 deficiency could lead to hyperphagia but also the therapeutic interventions to treat obesity in both genetic disorders." (PMID 29880780, 2018). "Generally speaking, all patients with PWS and PCSK1 deficiency, given the early onset of severe obesity, should receive nutritional and exercise advice to prevent excessive weight gain and the development of metabolic derangements, such as hypertension, type 2 diabetes, or dyslipidemia." (PMID 29880780, 2018). "PCSK1 is associated with obesity and diabetic nephropathy from previous GWASs and could be a T2D candidate gene." (PMID 26043787, 2015). "The first PCSK1 mutation, a compound heterozygous mutation, was identified in 1997, in a patient with obesity and hypogonadotropic hypogonadism (Gly483Arg and a donor splice site mutation in intron 5, causing skipping of exon 5 and the creation of a premature stop codon)." (PMID 25254043, 2014). "Further independent studies in different populations could help clarify the association of common variants in PCSK1 with obesity." (PMID 23451278, 2013). "Common single nucleotide polymorphisms (SNPs) in proprotein convertase subtilisin/kexin type 1 with modest effects on PC1/3 in vitro have been associated with obesity in five genome-wide association studies and with diabetes in one genome-wide association study." (PMID 23383060, 2013). "Three common SNPs in PCSK1 have been identified and associated with obesity." (PMID 23383060, 2013). "Furthermore, common PCSK1 variants (notably rs6232 and rs6234-rs6235) have been shown to contribute to obesity risk in a study of 13,659 European subjects." (PMID 23451278, 2013). "However, the presence of this functional variant should be considered as a serious risk factor for extreme forms of obesity in the Mexican population, as has been recently reported for heterozygous PCSK1 mutations in Europeans." (PMID 22737226, 2012). "Loss-of-function mutations in PCSK1 gene cause monogenic obesity and impaired glucose tolerance in human, implying that common variants in PCSK1 might predispose to obesity and type 2 diabetes in the general population." (PMID 20498726, 2010). "Mutation in the PCSK1 gene is sufficient to cause obesity, as this gene is part of a family of genes classified as responsible for monogenic obesity; in fact, alterations in this gene are associated with early onset obesity, severe intestinal malabsorption, and hyperphagia." (PMID 37761915, 2023).
Obesity (continued). "Similarly, obesity has been reported due to mutations affecting prohormone convertase 1 gene (PCSK1), one of the enzymes responsible for proteolytic cleavage of POMC to its neuroactive derivatives, either singly or as part the more complex genetic condition Prader–Willi Syndrome." (PMID 33233816, 2020). "Among the six leptin-associated loci, three genes (MC4R, BDNF, and PCSK1) are known to be involved in the hypothalamic leptin–melanocortin pathway, thus it is not surprising that those three loci are found to be associated with obesity-related traits and leptin levels in our pediatric setting." (PMID 29212175, 2017). "Similarly, two non-synonymous variants on PCSK1 were consistently associated with childhood and adult severe obesity in a study of 13,659 participants of European ancestry, making PCSK1 a candidate gene for polygenic obesity." (PMID 25825681, 2015). "Finally, we asked whether other common PCSK1 variants contribute to obesity in multi-ethnic American population." (PMID 23451278, 2013). "Thus, there is consistent evidence that the PCSK1 may be involved in mechanisms related both to protection from type 2 diabetes and risk of obesity." (PMID 21935364, 2011). "In this study, we aimed to examine whether the previously reported association of the PCSK1 genetic variants with obesity and related traits could be replicated in a population-based cohort of Chinese Hans including 3,210 unrelated individuals from Beijing and Shanghai." (PMID 20498726, 2010). "Mutations associated with monogenic obesity follow autosomal recessive (LEP, LEPR, POMC, and PCSK1) or autosomal dominant (MC4R, SH2B1, SIM1, GNAS) modes of inheritance." (PMID 41751424, 2026). "EMANATE aims to extend the indications of setmelanotide beyond biallelic POMC, PCSK1, and LEPR deficiencies, potentially addressing a broader spectrum of genetically driven obesity." (PMID 41212412, 2025). "In a Turkish study involving 105 children with early-onset obesity and analysis of 41 genes, approximately 10.5% of the variants were found in the SIM1, POMC, PCSK1, MC4R, and LEPR genes." (PMID 40149731, 2025). "Seven publications reported outcomes of MBS in patients with obesity caused by rare variants in LEPR, MC4R, NCOA1, PCSK1, POMC, SH2B1, or SIM1." (PMID 40560452, 2025). "We next examined the effect of mutations in individual genes on image- and biochemistry-based cardiometabolic outcomes, starting with the three autosomal recessive monogenic obesity genes: PCSK1, LEPR, and POMC." (PMID 39948378, 2025). "Key genes implicated in monogenic obesity include those involved in the leptin-melanocortin signaling pathway, such as MC4R, LEPR, PCSK1, and POMC, among others." (PMID 40281302, 2025). "It is specifically indicated for adult and pediatric patients aged 6 years and older with obesity caused by POMC, proprotein convertase subtilisin/kexin type 1 (PCSK1), or leptin receptor (LEPR) deficiency." (PMID 38540684, 2024). "Genetic susceptibility to obesity concerns only a fraction of the population and is the resultant of rare mutations in single genes (e.g., LEPR, PCSK1) or chromosomal abnormalities (e.g., Prader–Willi syndrome)." (PMID 39125772, 2024). "The drug is also indicated for obesity-related to proopiomelanocortin (POMC), proprotein convertase subtilisin/kexin type 1 (PCSK1), or leptin receptor (LEPR) deficiency." (PMID 39211725, 2024). "The other two are small molecules (glibenclamide to treat neonatal diabetes mellitus and setmelanotide to treat obesity associated with biallelic pro-opiomelanocortin (POMC), including PCSK1, deficiency obesity or leptin receptor (LEPR) deficiency obesity)." (PMID 38413985, 2024). "The mechanism involves a decrease in caloric intake and an increase in the expenditure of energy, ultimately contributing to the management of obesity in individuals with specific genetic conditions such as POMC, PCSK1, or LEPR deficiencies." (PMID 38540684, 2024).
Obesity (continued). "Setmelanotide is an effective medication for the disease of obesity in patients older than 6 years if the patient has POMC deficiency, PCSK1 deficiency, LEPR deficiency, or Bardet–Biedl syndrome." (PMID 37835041, 2023). "In patients with other rare genetic diseases of obesity, such as POMC, proprotein convertase subtilisin/kexin type 1 (PCSK1), or LEPR deficiency, notable impairments in quality of life have been reported." (PMID 36647077, 2023). "It is an MC4 receptor agonist developed for the treatment of obesity arising from POMC, proprotein convertase subtilisin/kexin type 1 (PCSK1), or LEPR deficiency." (PMID 37712012, 2023). "Setmelanotide was initially FDA-approved in 2020 for chronic weight management in individuals six years or older with obesity caused by POMC deficiency, proprotein subtilisin/kexin type 1 (PCSK1), or LEPR deficiency." (PMID 37937009, 2023). "The loss or impaired protease activity of PCSK1 (known as PC1 at that time) in particular has been reported in human and this led to high appetite causing obesity and diabetes." (PMID 35621394, 2022). "Setmelanotide (Imcivree) is a melanocortin-4 (MC4) receptor agonist used for the treatment of obesity due to proopiomelanocortin (POMC), proprotein convertase subtilisin/keying type 1 (PCSK1), or leptin receptor (LEPR) deficiency." (PMID 36232301, 2022). "This synthetic peptide was approved by FDA at the end of 2020 for treating obesity caused by genetic defects in pro-opiomelanocortin (POMC), leptin receptor (LEPR), or proprotein convertase subtilisin/kexin type 1 (PCSK1)." (PMID 36291616, 2022). "Recently, it was reported that heterozygous PCSK1 variants, causing partial PC1/3 deficiency, result in a significant increased risk for obesity." (PMID 36292633, 2022). "The first implication of PCSK1 in obesity arose from a patient with extreme childhood obesity described in 1995." (PMID 36292633, 2022). "Morbid early childhood obesity with normal development suggests leptin pathway gene mutation (LEP, LEPR, and PCSK1 mutations), if delayed development consider Prader-Willi syndrome or Bardet-Biedl syndrome." (PMID 35530907, 2022). "Genetic analyses showed that variants in the genomic regions of PCSK1 and PCSK2 associate with CVD traits, confirming previous reports about the involvement of these genes in obesity and diabetes, glucose homeostasis and insulin secretion." (PMID 36188622, 2022). "The US Food and Drug Administration approved the drug for chronic weight management in patients 6 years and older with obesity caused by POMC, PCSK1, and LEPR deficiency." (PMID 36232301, 2022). "The present work, therefore, focuses on the evaluation of the association of clinical markers related to obesity and SNPs of the LEP, LEPR, POMC, PCSK1, and MC4R genes in a healthy Mexican population." (PMID 35741707, 2022). "The genes in the top 2 enriched regions for monogenic obesity were Pomc, Pcsk1, and Lepr in ARH, and Sim1, Pomc, and Tub in THy/PHy." (PMID 34283813, 2021). "The extent to which heterozygous mutations/CNV in PCSK1 and POMC are involved in monogenic obesity remains a point of discussion." (PMID 32384097, 2020). "We identified six different novel variants within five obesity-related genes (SIM1, POMC, PCSK1, MC4R and LEPR) in seven out of 105 children with early-onset severe obesity in a Turkish population." (PMID 30991789, 2019). "Undoubtedly, the management of obesity is one of the most important (and challenging) therapeutic objectives in those patients with PWS and PCSK1 deficiency." (PMID 29880780, 2018). "Moreover, SNPs in or near PCSK1 loci may also contribute to obesity risk." (PMID 29132311, 2017). "Clinically, disruption of POMC, PCSK1, BDNF, and NTRK2 is associated with severe early-onset obesity." (PMID 25806089, 2015).
Obesity (continued). "The PCSK1 (Prohormone Convertase Subtilisin/Kexin type 1) gene is involved in regulation of appetite and consequently in obesity via the biochemical activities of its protein (PC1/3) on key peptides in the leptin-melanocortin pathway." (PMID 23451278, 2013). "In conclusion, our study has provided first insights of the modest contribution of common PCSK1 variation to obesity in multi-ethnic American population." (PMID 23451278, 2013). "In studies of European populations, PCSK1 represents the third most important gene contributing to extreme obesity." (PMID 23383060, 2013). "Recessive forms of obesity caused by homozygous / heterozygous compound loss of function mutations in five genes (LEP, LEPR, POMC, PCSK1 and MC4R) have been reported to date." (PMID 22043164, 2011). "At the same time, another obesity gene, PCSK1, was suggested using re-sequencing of linkage peaks, and some replication studies have established week associations between this gene and obesity related measures." (PMID 21912638, 2011). "This is the first study to report the significant SNP-gender interactions of the PCSK1 rs6234 on obesity related traits in Chinese Hans." (PMID 20498726, 2010). "This patient’s elevated body mass index of 31 kg/m2 and family history of obesity support this connection, suggesting PCSK1 may play a role in his phenotype." (PMID 40724652, 2025). "Setmelanotide is another anti-obesity medication; however, it has been approved only for three ultra-rare genetic disorders that cause obesity: Pro-OpioMelanoCortin (POMC) deficiency, Proprotein Convertase Subtilisin and Kexin type 1 (PCSK1) deficiency, and LEPtin Receptor (LEPR) deficiency." (PMID 40806889, 2025). "Important genes associated with monogenic obesity consist of leptin (LEP), leptin receptor (LEPR), proopiomelanocortin (POMC), prohormone convertase 1 (PCSK1), MC4R, single-minded homolog 1 (SIM1), brain-derived neurotrophic factor (BDNF), and its receptor NTRK2 (commonly referred to as TrkB)." (PMID 40428329, 2025). "The recent approval of Setmelanotide, an MC4R agonist, for treating obesity caused by deficiencies in proopiomelanocortin (POMC), proprotein convertase subtilisin/kexin type 1 (PCSK1), or Leptin Receptor, has heightened scientific interest in the effects of MCRs on feeding and energy balance." (PMID 39974186, 2025). "Setmelanotide, a highly selective MC4R agonist with a preferential Gqα/G11α pathway stimulation, is approved for specific causes of monogenic obesity upstream of the MC4R (pro-opiomelanocortin deficiency, proprotein convertase subtilisin/kexin type 1, leptin receptor deficiency)." (PMID 39104441, 2024). "The first one, setmelanotide, was approved in 2020, and it is used in patients with POMC, PCSK1, or leptin receptor (LEPR) deficiencies, which result in insufficient activation of the MC4R and, consequently, cause excessive appetite and severe obesity developing in early childhood." (PMID 39125772, 2024). "In addition, mutations in the POMC gene and in the PCSK1 gene, which encodes an endopeptidase that plays a critical role in POMC processing, also result in severe forms of obesity." (PMID 39876968, 2024). "Overall, the study concluded that heterozygous variants involving PCSK1, POMC, LEP, and LEPR are common among adult patients with class III obesity and occasionally may exhibit a phenotype similar to that of homozygotes." (PMID 37835041, 2023). "The present study aimed to identify associations linking allelic variants of the PCSK1, TMEM18, GPX5, ZPR1, ZBTB16, and PPARG1 genes with anthropometric and biochemical traits and metabolic diseases (obesity or metabolic syndrome) in an adult population from northwestern Mexico." (PMID 37761915, 2023). "Reported associations between PCSK1 allelic variants (rs6232 and rs6235) in European-American (OR: 1.71, p: 0.018) and African-American (OR: 1.47, p: 0.018) individuals and obesity, but not in Hispanic individuals." (PMID 37761915, 2023).